CCDC81 (coiled-coil domain containing 81)
Synonyms: FLJ16339; FLJ23514
Tractability: Antibody: its Gene Ontology location is reachable by antibodies, with high confidence.
Gene: Protein-coding gene on chromosome 11 (86,374,736 to 86,423,109, forward strand). Ensembl gene ENSG00000149201.
Subcellular location: Cytoplasm, cytoskeleton, microtubule organizing center, centrosome
Subcellular location (Human Protein Atlas): Basal body; Plasma membrane
Gene Ontology:
Molecular function: protein binding
Cellular component: centrosome; ciliary basal body; microtubule organizing center
Genetic constraint (gnomAD): Loss-of-function variants: 62 observed, 68.12 expected, observed/expected ratio (o/e) 0.91, 90% interval 0.74 to 1.12. The upper end of that interval is the gene's LOEUF score, 1.12, which puts it in group 4 of 6, group 1 being the genes least tolerant of losing a copy. Missense variants: 655 observed, 687.21 expected, observed/expected ratio (o/e) 0.95, 90% interval 0.89 to 1.02. Synonymous variants: 211 observed, 249.45 expected, observed/expected ratio (o/e) 0.85, 90% interval 0.75 to 0.95.
Homologues: Orthologues: chimpanzee CCDC81 (98% identical), macaque CCDC81 (96% identical), rabbit CCDC81 (85% identical), dog CCDC81 (82% identical), pig CCDC81 (81% identical), rat Ccdc81 (79% identical), mouse Ccdc81 (79% identical), guinea pig CCDC81 (77% identical), tropical clawed frog ccdc81 (49% identical).
Diseases named in the same sentence as CCDC81 in open-access papers:
CCDC81 is named in the same sentence as 2 diseases in open-access papers, as found by Europe PMC text mining. Sharing a sentence is not in itself a finding about the gene and the disease. The quoted sentences say what the papers report.
breast tumors (1 paper, 2013). "Besides genes that are hypermethylated only in breast tumors (compare with breast normals), users can also find genes that are hypermethylated only in endometrial tumors (compare with endometrial normals) (such as CCDC81), and in both tumors (such as SOX11)." (PMID 23630576, 2013).
CCDC81 also shares sentences with these, for which no sentence is quoted: endometrial tumors (1 paper).